LEP (leptin)
Diseases named in the same sentence as LEP in open-access papers (continued):
Sharing a sentence is not in itself a finding about the gene and the disease.
tumor (continued). "High insulin and leptin levels seem to have a role modulating the growth of these tumours." (PMID 27415018, 2016). "Furthermore, expression of leptin was greater in the breast tissues adjacent to the tumor compared to tumor specimens." (PMID 27293305, 2016). "Normal and tumor cells respond to metabolic hormones, such as leptin and insulin." (PMID 27842582, 2016). "Macrophage depletion significantly reduced leptin-induced tumor volume (P < 0.05) and tumor weight (P < 0.01), improved survival (P < 0.05), attenuated leptin-mediated exacerbation pulmonary metastasis (P < 0.01), and decreased leptin-stimulated expression of IL-8 and Ki67 in the tumor (P < 0.05)." (PMID 27588409, 2016). "Moreover, leptin is able to shape the tumor microenvironment within the mammary gland by inducing multiple concurrent events such as migration of endothelial cells, angiogenesis and recruitment of macrophages and monocytes." (PMID 26556856, 2016). "Furthermore, we found that JAK/STAT-PI3K/AKT pathway should be responsible for the pro-tumor effects of leptin." (PMID 27863383, 2016). "In fact, AT is recognized now as potent endocrine organ by secreting pro-inflammatory cytokines [such as tumor necrosis factor-alpha (TNF-α) and interleukin-6 (IL-6)] and adipokines (such as leptin) in the tumor microenvironment, with great significant impact on both tumor and immune cells." (PMID 27066006, 2016). "Our results suggest that leptin/leptin receptor signaling may represent a potential therapeutic target that can block the stromal-tumor interactions driving BCSC-mediated disease progression." (PMID 26556856, 2016). "However, our results in leptin-treated macrophages reveal the opposite for NFκB although confirm the upregulation of pSTAT3 observed by these authors in tumor cells exposed to leptin." (PMID 25599228, 2015). "Interestingly, inhibition of autophagic process by treatment with inhibitors and LC3B gene silencing blocked leptin-induced increase in cell number and suppression of apoptosis, indicating a crucial role of autophagy in leptin-induced tumor progression." (PMID 25704884, 2015). "Tumor-derived molecules, peptides/neuropeptides, neurotransmitters and hormones as leptin and GH-relin may interact with cytokines in the generation/development of the cachexia process." (PMID 26337554, 2015). "This is probably due to the well-known fact that pro-carcinogenic effect of leptin and anti-carcinogenic effect of adiponectin could be interrelated to the inflammatory response and cell proliferation in the tumor microenvironment." (PMID 26431176, 2015). "To further investigate other plausible roles of leptin on macrophages, we examined whether acting in the tumor microenvironment or systemically, this adipokine might modulate macrophages M1/M2 activation." (PMID 25599228, 2015). "Furthermore, reducing leptin levels in obASCs also resulted in a reduction in tumor volume and fewer metastatic lesions in the lung and liver of SCID/beige mice." (PMID 26286584, 2015). "Serum leptin levels could be mainly contributed by adipocytes from the tumor microenvironment and other adipose locations in obese mice containing larger fat masses." (PMID 25599228, 2015). "We first investigated the effect of leptin on tumor growth in." (PMID 25704884, 2015). "In fact, its specific inhibition greatly decrease the peritumoral adipose tissue effect on EAC cells gene expression, suggesting that several factors could influence tumor behavior via a synergistic action that is partially driven by leptin." (PMID 25857300, 2015). "Of note, we have demonstrated that leptin acting as a mediator of tumour /stroma interaction within tumour microenvironment may promote mammary carcinogenesis 8,17." (PMID 25721149, 2015). "Based on previous reports, it would be possible that autophagy induction plays a role in leptin-induced tumor invasion and this hypothesis remains to be further investigated." (PMID 25704884, 2015).
tumor (continued). "In this study, we hypothesized that leptin-induced tumor growth could be mediated by autophagy activation." (PMID 25704884, 2015). "One mechanism underlying this relationship may depend on the local secretion of adipokines, specifically leptin, and their paracrine effect on tumor behavior." (PMID 25857300, 2015). "In addition, both leptin and adiponectin levels were also significantly lower in the tumor tissue compared to the tissues adjacent to the tumor (leptin, p = 0.027; adiponectin, p = 0.0023)." (PMID 26431176, 2015). "However, higher intensity of staining was seen for leptin in the tumor than in the tissues adjacent to the tumor as shown in the earlier studies." (PMID 26431176, 2015). "Treatment with the PEG-LPrA2 leptin antagonist was associated with a non significant tendency to reduce tumor progression in obese and overweight mice but not in lean ones." (PMID 25599228, 2015). "We investigated whether body weight increase and modulation of leptin signaling might affect macrophage recruitment/activation and tumor progression." (PMID 25599228, 2015). "As stated by Garofalo and Surmacz (2006), it is possible that the local leptin concentration and signalling could be involved in the stimulation of tumour progression." (PMID 26508818, 2015). "Interestingly, these patients had higher plasma leptin levels, particularly the ones with ER-negative tumour phenotype." (PMID 25482303, 2014). "Activation of leptin-signaling results in concurrent activation of multiple oncogenic pathways leading to increased proliferation, acquisition of mesenchymal phenotype, enhanced migration, and invasion of tumor cells." (PMID 25505738, 2014). "Leptin is known to be angiogenic and to modulate tumor growth by increasing VEGF expression." (PMID 25356654, 2014). "Leptin levels positively correlate with ER expression and BC tumor size." (PMID 25360510, 2014). "The exception was tumor size, which was shown to be associated with OBR and leptin expression." (PMID 23425972, 2013). "The present setting, using model on tumour sites distant from the adipose tissue, might try to partially reconstruct the microenvironment of tumours in presence of plasmatic levels of leptin and adiponectin similar to those of overweight or obese patients." (PMID 23554900, 2013). "Leptin can further contribute to tumor angiogenesis via induction of MMPs and integrin expression." (PMID 24202338, 2013). "These mice lacked leptin and other adipokines, but tumor growth was linked to effects elicited by insulin resistance and inflammation." (PMID 24202338, 2013). "This hypothesis is in agreement with the critical role of the leptin in mediating intestinal inflammation and tumor growth." (PMID 23737651, 2013). "Data from paracrine effects of leptin in vitro may still be considered speculative since a study on tumor development using the fatless A-Zip/F1 mouse model showed a different conclusion." (PMID 24202338, 2013). "Leptin actions in tumor angiogenesis could amplify, be redundant and/or compensatory to VEGF signaling." (PMID 24202338, 2013). "The imbalance between adiponectin and leptin in SE mice may be one of the factors contributing to tumor aggressiveness." (PMID 23272114, 2012). "Pretreatment of serum with leptin-neutralizing antibody significantly inhibited tumor cell growth." (PMID 23272114, 2012). "Perhaps this decrease may have maintained a balance between serum adiponectin and leptin levels, and possibly contributed to the tumor inhibition observed in EE mice." (PMID 23272114, 2012). "Leptin, which may be controlled by specific stimulation of the brain via EE or psychological intervention, has significant influence on tumor growth." (PMID 22263109, 2012). "The limited published animal studies trying to find whether leptin promote tumor growth have reported different results." (PMID 21338489, 2011).
tumor (continued). "Although all the mechanism(s) by which leptin contributes to tumor development are unknown, it appears leptin stimulates an increase in cell numbers, and the expression of VEGF/VEGFR-2." (PMID 21731759, 2011). "For example, leptin increases EC expression of pro-inflammatory/-thrombotic mediators, enhances platelet aggregation in vitro and promotes inflammatory angiogenesis during tumour growth." (PMID 21533119, 2011). "The overexpression of the leptin system could lead to leptin-enhanced tumor growth and progression under hypoxic conditions." (PMID 20569445, 2010). "Leptin levels decreased gradually with tumor stage and aggressiveness." (PMID 21254741, 2010). "Nevertheless, these data suggest that targeting leptin/OB-R functions may negatively impact tumor growth, angiogenesis, apoptosis, and expression of inflammation-related factors and could impair leptin-growth promoter-factor crosstalk in human BC." (PMID 19531256, 2009). "Taken together, the present data support a role for leptin as a tumor growth factor." (PMID 19531256, 2009). "Leptin may also promote tumor cell survival in xenograft models via increased expression of E-cadherin." (PMID 18945363, 2008). "By raising SHBG, improving leptin sensitivity, and decreasing excess insulin-mediated signalling, nutritional and therapeutic ketosis may attenuate this endocrine, paracrine and autocrine growth axis and re-sensitise tumour cells to apoptotic initiation." (PMID 41586225, 2025). "To determine whether there is a correlation between patients' socio-demographic data and the biological variables analyzed, we identified that an increase in leptin expression correlates with larger tumor size (p = 0.042) and greater difficulty of surgical dissection (p = 0.001)." (PMID 41255618, 2025). "Interestingly, leptin enhanced the IL36G expression in tumour cells in our in vitro study." (PMID 40268791, 2025). "Thus, to the best of our knowledge, in this study, we report for the first time the predictive value of the immunohistochemical (IHC) status of leptin, leptin-R, adiponectin, and resistin together on tumor characteristics and outcomes in a cohort of 81 RCC patients who were treated with nephrectomy." (PMID 41010935, 2025). "Leptin is thought to promote tumor growth, while adiponectin may have tumor-suppressing properties." (PMID 41255618, 2025). "Additionally, IL-6, TNF-α, CXCL12, and leptin are considered to significantly promote tumor cell migration and proliferation, as well as inhibit apoptosis and activate autophagy, facilitating the development of tumor bone metastasis." (PMID 38571500, 2024). "Therefore, damage to the hypothalamus during cranial tumor surgery may likely disrupt the function of leptin, resulting in hyperphagia and reduced metabolic rate." (PMID 39502571, 2024). "Although leptin eventually does not modify autophagy or proliferation of triple-negative cells, basal levels of autophagy active in these cells could participate in other leptin-induced tumor characteristics, as we will describe regarding metabolism and cellular migration." (PMID 38228661, 2024). "Leptin, mainly secreted by adipose tissue, is known to regulate several physiological processes, including energy metabolism, reproduction, appetite control, and immunity, but its direct biological effects on tumor development and progression have also been reported." (PMID 37509120, 2023). "Prior studies have noted the ability of CAAs in secreting high abundance of IL-6, IL-1β, CCL2, chemokine (C–C motif) ligand 5 (CCL5), tumor necrosis factor-α (TNF-α), vascular endothelial growth factor (VEGF) and leptin, which could enhance tumor invasion and immune escape." (PMID 37127625, 2023).
tumor (continued). "Upon “in vitro” leptin stimulation, there is an increase in the expression of miR-21, miR-96, miR-31, and miR-182, reported to have oncogenic actions which have been reported, such as oncogenic miRNAs; in addition, leptin reduces tumor suppressor miRNAs (miR-143, miR-26b, miR-27b, miR-489)." (PMID 36674935, 2023). "In addition, LEP was also over-expressed in tumor epithelium than in normal epithelium." (PMID 36941557, 2023). "In addition, leptin is able to support the lamellipodia formation and tumor cell invasion through activation of cell division control protein 42 (Cdc42) and Ras-related C3 botulinum toxin substrate 1 (Rac1) in human tumor colorectal cell lines LS174T and HM7." (PMID 37760840, 2023). "However, whether and how the leptin signalling pathway is affected by primary BC tumour to exert systemic regulation is still unknown yet." (PMID 37620316, 2023). "In addition, leptin acts like mitogens by inhibitingapoptosis and increasing tumor development." (PMID 38152619, 2023). "Thus, leptin-mediated signaling does not account for why VSG is less effective in reducing tumor burden compared to weight loss alone." (PMID 35775614, 2022). "In addition to leptin produced by tumor cells, we speculate that interaction between ECs and adipose cells in the tumor microenvironment accounts for dysregulation of leptin." (PMID 36381236, 2022). "Furthermore, leptin and its receptor were expressed in 37% and 51% of PTC tissue and lymph node metastases, respectively, vs. non-tumor tissue, and expression was associated with greater neoplasm size and lymph node metastases." (PMID 35158824, 2022). "However, its expression was associated with tumor expression of prostaglandin 2 (PGE2) and leptin." (PMID 36262532, 2022). "Moreover, serum glucose (R2 = 0.22, p < 0.01) and leptin (R2 = 0.22, p < 0.01) levels was associated with tumor volume, while no such association was observed for insulin." (PMID 35361802, 2022). "Therefore, the implementation of a treatment that reduces the blood levels of leptin or inhibits the cascades of signalling dependent on this adipokine may limit the development of neoplastic disease." (PMID 35628118, 2022). "However, AAV-Leptin administration after advanced tumor development causes loss of body weight without affecting tumorigenesis and survival." (PMID 35563777, 2022). "Leptin could inhibit T cell responses by modulating both tumor cells and the TME." (PMID 34202969, 2021). "In addition, there were a few studies that showed that it may also promote tumor growth directly or indirectly through inflammatory pathways, leptin, and adiponectin." (PMID 33777737, 2021). "In addition, a carcinogenic role of leptin in the tumor microenvironment was discovered." (PMID 33799880, 2021). "Moreover, was observed that, independently of the tumor subtype, a mean of 81 ± 2.5% of the tumor inflammatory mononuclear cells presented to be positive for the leptin staining (mean IHC score of 2.0 for the macrophages and mean IHC score of 1.6 for the lymphoid cells)." (PMID 33644151, 2021). "Therefore, leptin and its receptors could be promising therapeutic targets to overcome tumor immunosuppression in the disease." (PMID 34202969, 2021). "Interestingly, adiponectin and leptin exhibit opposite roles in tumor growth." (PMID 33226729, 2021). "Indeed, leptin was shown to be a strong inductor of tumor accumulation of MDSCs, and the availability of FAs in the TME could feed FAO that is necessary for the immunosuppressive activity and tumor promotion of MDSCs." (PMID 33917351, 2021). "Therefore, the fact that both the tumor cells and the activated immune cells prefer glycolysis over OXPHOS could be associated with the inhibition of leptin synthesis, which can be regarded as an indicator of the state of energy production." (PMID 33809200, 2021). "In addition, leptin is secreted by tumor cells that also overexpress its receptors." (PMID 34202922, 2021).
tumor (continued). "After ruling out LEP as a potential biomarker using TCGA analysis, we found that higher PPFIA4 levels were associated with primary tumor, higher stage (II-IV), and higher N stage (referring to a higher number of lymph node metastasis adjacent to tumor in the TNM staging system)." (PMID 34094943, 2021). "Furthermore, we hypothesised that the concentrations of YKL-40, leptin, and adiponectin and TF activity can vary according to the molecular subtype, tumour diameter, nodal status, staging, grading indexing, and histological subtypes of BrC." (PMID 32512860, 2020). "In addition, blocking leptin signaling using a full-length leptin receptor (ObR) antagonist also reduced mammosphere formation indicating a potential therapeutic target to block stromal-tumor interactions driving breast CSC-mediated disease progression." (PMID 33339340, 2020). "Therefore, the influence of leptin on NK cell cytolysis may depend on the tumor target cells, most likely based on their differential NK cell ligand profile." (PMID 32231659, 2020). "In addition to the earlier studies indicating that neutralizing GM-CSF reduced the proliferation, angiogenesis, and colonic epithelial cells (CECs) in neoplasia, our data point out that this factor is also an accessory after the fact along with leptin and prolactin." (PMID 31742371, 2020). "Interestingly, leptin, through canonical ObR signaling activation, has been identified as a monocyte/macrophage chemoattractant and inducer of macrophage functions with potential relevance to their tissue accumulation and tumor-promoting effects." (PMID 32260113, 2020). "Furthermore, circulating YKL-40, leptin, and adiponectin concentrations and TF activity have not been associated with other prognostic indicators, such as tumour grade and TNM stage or tumour size and nodal status." (PMID 32512860, 2020). "In addition, a similar study by another author found that leptin was associated with a decrease in apoptosis in Ishikawa cells; thus it is feasible to consider the notion that leptin may have a role to play in tumor proliferation, growth, and survival." (PMID 32742493, 2020). "In addition, leptin was significantly higher in advanced BC with LN invasion, which demonstrated that it might play a role in the tumor metastasis." (PMID 30702563, 2019). "Therefore, we evaluated whether leptin induces the expression of these two TFs in a cellular model of non-tumor mammary epithelium." (PMID 31554180, 2019). "Thus, excessive leptin signaling might be involved in neoplasia and metaplasia in the stomach, mediated by the STAT3-HIF-1-Hes-1 axis." (PMID 31141984, 2019). "Adoptive transfer or activation of iNKT cells in obese mice reduced body weight, decreased triglyceride and leptin levels while increasing the production of anti-inflammatory cytokines that could counterbalance the meta-inflammatory state and enhance the anti-tumor immune response." (PMID 31475003, 2019). "Hence, we concluded that therapeutically targeting communication between tumor and muscle, such as inhibiting leptin signaling, could provide a more efficient treatment than targeting muscle or myostatin." (PMID 30718259, 2019). "Also, in hematologic neoplasms, such as MM, leptin was revealed to have pro-tumour effect." (PMID 31334678, 2019). "Therefore, the decrease in leptin levels in exercised obese mice may suppress inflammation that would otherwise permit the occurrence of a critical initial phase of tumor development." (PMID 31528182, 2019). "Leptin is a satiety hormone acting in the hypothalamus to reduce hunger, but other studies have described pro-inflammatory, anti-apoptotic, and pro-angiogenesis actions of this hormone, indicating that it plays an important role in the stimulation of tumor growth." (PMID 31528182, 2019).